CD68 (CD68 molecule)
Diseases named in the same sentence as CD68 in open-access papers (continued):
Sharing a sentence is not in itself a finding about the gene and the disease.
tumor (continued). "While CD68 and CD163 are widely used surrogate markers to investigate macrophage polarity and characterize tumor-associated macrophages, the binary classification of macrophages into M1 and M2 polarized activation states is overly simplistic." (PMID 39456610, 2024). "RG7155 potently inhibited the viability of CSF-1-differentiated macrophages in vitro and reduced the number of CD68+ CD163+ TAMs in tumor biopsies from diffuse-type giant cell tumor patients." (PMID 39516356, 2024). "To experimentally verify immune cell dysfunction, we performed digital spatial profiling (DSP, GeoMx) of tumour-infiltrating myeloid cells (CD68) using a targeted immunobiology panel (78 genes)." (PMID 37758326, 2024). "An association between high CD68+ TAM infiltration in the TME and high TNM stage, increased tumor size and shorter patient survival were also reported." (PMID 39044824, 2024). "In the same study, CD68+ macrophages in tumor stroma positively correlated with tumor size and were an independent factor for reduced BC specific survival." (PMID 39044824, 2024). "Additionally, while the current study focused on the CD68+ macrophage population, further research should include specific markers for different subsets of tumor-associated macrophages, such as M1 and M2 macrophages, to better understand their distinct roles in tumor biology." (PMID 39330005, 2024). "In analyzing only the stromal compartment, a significant (p = 0.017) decrease in the CD68 cell density in tumor resection specimens post RCT (mean LI: 9.9 (±8.1)) was observable compared to the pre-therapeutic biopsies (mean LI: 18.1 (±15.5))." (PMID 38474362, 2024). "CD68+ showed considerable macrophage infiltration of the tumor, suggesting the process of elimination of the tumor probably by an immune-mediated process." (PMID 39861800, 2024). "A decrease in CD68+ macrophages between screening and cycle 1 day 15 was observed in tumor tissue from all three patients." (PMID 38501219, 2024). "Tumor associated macrophage showed significant positive correlations with CCL2 (cor = 0.095, P = 3.41E−02*), CD68 (cor = 0.178, p = 6.79E−05*), and IL10 (cor = 0.219, p = 9.38E−07*)." (PMID 39030403, 2024). "Histologisch zeigte sich, dass der Tumor aus dicht gelagerten großen histiozytenartigen Zellen mit Expression von Vimentin, CD68 und CD163 sowie Negativität für Keratin, Langerin und SMA aufgebaut ist." (PMID 38472383, 2024). "MPO+ neutrophils and CD68+IDO1+ tumor-associated macrophages (TAMs) were enriched in the epithelial compartment, and myeloid lineage cells were located nearest to tumor cells." (PMID 38951801, 2024). "CD68+CD163+ TAM frequency was studied alongside the frequency of tumor infiltrating lymphocytes (TILs) in TNBC patients." (PMID 39044824, 2024). "Multiplex IHC staining assays demonstrated a higher abundance of apoptotic tumour cells (CASP3+PanCK+) surrounded by macrophages (CD68), NK cells (CD56), and plasma cells (IgG) in EBVhigh-TCA compared to EBVlow-TCA." (PMID 39231979, 2024). "BMMF Rep expression in the tumor‐adjacent mucosa of CRC patients was observed for 99% of patients (TMA cohort) and was linked to Rep+ M2 CD68+ interstitial Mfs (IF analyses), which were almost completely absent in mucosal tissues of non‐CRC healthy controls." (PMID 36811271, 2024). "Three tumor-associated macrophage (TAM) markers, MSR1/CD204, CD86, and CD68, exhibited a 6-fold (p < 0.0001), 8.9-fold (p < 0.0001), and 15.6-fold increase in mRNA expression levels, respectively, in LGG tumors." (PMID 38539537, 2024). "In contrast, in tumor‐adjacent tissues, the curves with high CD68 POS located at high incidence for CRC‐specific death (no clear order for non‐CRC‐specific death)." (PMID 36811271, 2024). "The cell density of CD68 in tumor showed a clear tendency to be significantly higher in ADC than SQCC (p = 0.062)." (PMID 38424363, 2024).
tumor (continued). "Within the same tissue area, CD163+ TAMs showed significant spatial correlations exclusively with CD68+ monocytes/macrophages (tumor: r = 0.42, P = 6 × 10−3; stroma: r = 0.43, P = 4 × 10−2; Pearson), confirming their subset classification as CD68+ cells." (PMID 38407373, 2024). "We observed a rise in MALAT1 expression, correlating with increased levels of monocyte chemoattractant protein-1 (MCP-1) and CD68, CD163, CD206, indicative of tumor-associated macrophages in lung tumors of AA patients." (PMID 38791954, 2024). "In tumor tissues, curves with high CD68 POS are located at low incidence for CRC‐specific death (no clear order for non‐CRC‐specific death)." (PMID 36811271, 2024). "Among these, CD68 was found on all macrophages and monocytes, whereas CD163 is a high-affinity scavenger receptor and a marker of tumor-associated M2 macrophages." (PMID 39272860, 2024). "The colocalization of CD11c with PD-L1 and of CD68 with PD-L1 was initially assessed using multicolor immunohistochemistry (mIHC) in TLSs from 8 randomly selected tumor samples in the immunochemotherapy group." (PMID 39726591, 2024). "The expression of specific TAMs, such as CD47, CD68, and CD163, has been studied in NPC and is linked to various aspects of tumor behavior, prognosis, and potential therapeutic strategies." (PMID 39682556, 2024). "As previously reported, Probio-M9 substantially reduced the inflammatory response, infiltration of CD68+ macrophages in the non-tumor area, expression of TNF-α and IL-6, and number of Ki67-positive proliferating cells in the tumor area." (PMID 38540144, 2024). "Histologically, the tumor was found to consist of densely clustered large histiocyte-like cells with expression of vimentin, CD68, and CD163 as well as negativity for keratin, langerin, and SMA." (PMID 38472383, 2024). "Using the Kaplan-Meier method and Cox proportional hazard regression model to assess the correlation between cell type infiltration and OS, we observed that high infiltration of CD68+SHP2+ TAMs in tumor correlated with poor OS (P = 0.048)." (PMID 38799432, 2024). "By reducing tumor-favorable microenvironment factors such as CD68+ macrophage infiltration and changes to the profile of cytokines released by macrophages in the TME, Ad-ANGPTL4 treatment considerably reduced the development of HCC.." (PMID 38997297, 2024). "Increased CD-3, CD-4, and CD-68 staining occurred in the tumor transplant area around the regions of tumor necrosis in immune-reconstituted TPV/eGFP subjects when compared to immunocompromised TPV/eGFP-treated mice." (PMID 39200298, 2024). "The tumor-infiltrating macrophages (defined as CD68+ cells) also displayed heterogeneous responses to concurrent chemoradiotherapy (CCRT)." (PMID 38654284, 2024). "Rep was expressed in the tumor‐adjacent mucosa of 99% of CRC patients (TMA), was histologically associated with CD68+/CD163+ macrophages and was increased in CRC patients when compared to healthy controls." (PMID 36811271, 2024). "In the current study, the tumor that presented progression had round–oval cell predominance with abundant CD68+ and CD163+ macrophages." (PMID 39335193, 2024). "Co-staining of HSD11B1 with CD68+ cells confirmed that HSD11B1 was expressed in tumor-infiltrating macrophages." (PMID 38170044, 2024). "The major method originally applied for the identification of TAMs in human tumor tissue was immunohistochemistry (IHC) with anti-CD68 antibodies." (PMID 39516356, 2024). "Compared with non-responders, patients with a partial response showed a significantly lower risk of relapse when their residual tumor exhibited high FOXP3, CD68, CD83, CD31 and CD34 content and IL15 expression but a low CD138 concentration." (PMID 37511057, 2023). "On the other hand, the mass channels of 165.0 m/z Hydroquinone, 41.0, 42.0, 167.0 m/z lipid fragments, and 131 Asparagine exhibited higher expression in tumor cells compared to CD68+ cells in the proximity of CD31+ endothelial cells." (PMID 38086839, 2023).
tumor (continued). "Within the tumor microenvironment, myeloid cells were predominant, represented by CD11c+ DCs (3.13%) and CD68+ macrophages (0.33%), while T lymphocytes accounted for only 0.16%." (PMID 38274817, 2023). "CD68+ and CD163+ cells identify macrophages and in line with that also tumor-associated macrophages (TAMs), which are known to be present in high numbers in glioblastomas." (PMID 37543970, 2023). "We focused on the macrophage and monocyte CD68+ and CD66b+neutrophils that were attracted to the tumor by cytokine during inflammation." (PMID 37584750, 2023). "We also assessed Cd68 mRNA level in tumor as a marker for monocytes, including circulating and tissue macrophages." (PMID 37342258, 2023). "Considering the expression of ACT1 in both intestinal epithelium and immune cells, we next detected the distribution of ACT1 and CD68+ macrophages in the tumor tissues of CRC patients." (PMID 36978108, 2023). "In this study, we found positive associations between high CD68 + TAM/CD163M2-like TAM numbers and higher tumour grade in the Luminal-B group." (PMID 36622544, 2023). "In cutaneous malignant melanoma, MT overexpression was found to be related to the presence of tumor-infiltrating CD68+ macrophages." (PMID 38023247, 2023). "Although CD68+ TAMs infiltration in the tumor was significantly associated with poor OS and DFS, the survival data of CD68+ TAMs in TS and TN were reversed." (PMID 36633963, 2023). "We firstly tested immunologic markers of CD4+, CD8+, CD68+, FOXP3+, PD‐L1+, CD4+FOXP3+, CD4+FOXP3−, CD68+PD‐L1+, CD68+PD‐L1−, CD8+PD‐L1+, and CD8+PDL1− in the tumor core area, tumor‐associated stroma area, and total area before NAC." (PMID 36043478, 2023). "The low-grade group showed significantly more CD68+ macrophages in both the tumor and total region than the high-grade group." (PMID 38023213, 2023). "To further evaluate the existence of C16, we stain CD3+ CD45+ CD68+ CD11B+ cells for single-cell suspension of paired tumor and peri-tumor tissue." (PMID 36845133, 2023). "The CD68+ cells infiltrating PAs were positively correlated with tumor volume (p = 0.03, r = 0.21) and Knosp grade (p = 0.003, r = 0.29)." (PMID 36831707, 2023). "CD68 isexpressed on the membrane of both M1 and M2 macrophages, and the marker CD163 hasbeen used to identify tumor-associated macrophages (TAM)." (PMID 36880147, 2023). "The amount of Iba1+ and CD68+ cells correlated with each other and the tumor size, i.e., bigger tumors contained more Iba1+ and more CD68+ macrophages." (PMID 37996600, 2023). "Pembrolizumab monotherapy, which targets the PD-1 protein, cannot elicit an effective immune response in most GBM patients, likely due to the low number of T cells within the tumor microenvironment and the abundance of CD68 + macrophages." (PMID 37525217, 2023). "GC in GC tumour of the bone have frequently been found to show immunoreactivity for CD68; this was confirmed by our study, as all analysed GCs of these lesions stained positive for the antigen." (PMID 37509363, 2023). "CD68+ is the first interacting cell with the greatest capacity to migrate to the tumor and interact with CD3, CD8 and CD20." (PMID 38219446, 2023). "Accordingly, activation of NICD in mice led to repressed tumor growth and in clinical settings, higher grade lung biopsies were shown to have less of Hes1+CD68+ cells indicative of an immunosuppressive TME." (PMID 38269089, 2023). "The CD68-positive cells (macrophages) (median of 648/mm2 (IQR 235–727/mm2)) outnumbered the CD45-positive cells (median of 242/mm2 (IQR 58–366/mm2)) in the tumor micro-environment before treatment." (PMID 37572156, 2023). "Our aim was to investigate some of the main components of the cellular immune response in TME—tumor-infiltrating cytotoxic T cells (Tc, CD8+) and tumor-associated macrophages (TAMs, CD68+)—in patients with CC." (PMID 37109686, 2023).
tumor (continued). "Compared to adjacent normal brain tissue, MS4A7 was typically enriched in GAMs within the tumor mass, with close relation to macrophage/microglia marker CD68 and M2 marker CD163." (PMID 36944954, 2023). "Both HBx and CD68, as well as MVI and tumor size, were independently associated with worse OS and PFS of patients with HBV-related HCC in the training cohort." (PMID 37370037, 2023). "In the tumor areas, we solely detected CD68 corresponding to the infiltrating and activated macrophages (CD68+/pSTAT3+)." (PMID 37762522, 2023). "Tumor-associated macrophages (TAM) indeed represent a critical component of the tumor immune microenvironment, and are characterized by the expression of CD68." (PMID 37086293, 2023). "Tumor progression can result from an increased proportion of M2-like TAMs containing CD68+ and CD163+." (PMID 37894541, 2023). "The mass channels of 61.0, 60.0, 77.0, and 28.0 m/z yielded high expression in CD68+ cells compared to tumor cells consistently." (PMID 38086839, 2023). "Although the expression levels of HBx and CD68 varied widely among all tumor samples, HBx expression was demonstrated to be strongly correlated with CD68 in human HBV-related HCC tissues, with a Pearson’s coefficient of 0.38 (P < 0.0001)." (PMID 37370037, 2023). "By TCGA and TISIDB analysis, we noticed the downregulation of Act1 expression in tumor tissues of CRC patients negatively correlated with accumulated CD68+ macrophages in the tumor." (PMID 36978108, 2023). "As confirmed by our data, the GCs in tenosynovial GC tumour have also been documented to shown CD68-immunoreactivity, as do macrophages in the tumour tissue." (PMID 37509363, 2023). "In the tumor associated stroma, the proportion of DAB2+ (fold change 4.64, p = 0.029), CD68+ (fold change 2.04, p = 0.02) and DAB2+ CD68+ (fold change 3.15, p = 0.028) was significantly increased in metastatic compared to matched primary tumors." (PMID 37815603, 2023). "In recurrent GBM, the predominant markers were HLA-DR and CD68, present both in the center and in the periphery of the tumors, while CD11c was found only in the center of the tumor." (PMID 37370866, 2023). "Compared with the adjacent normal tissues, the tumor tissues showed significantly higher CD68/CD3 and FOXP3/CD8 ratios, representing a more immunosuppressive phenotype in PDAC." (PMID 36900182, 2023). "In a large cohort of 38 pathologic specimens, tissue microarray analysis demonstrated a paucity of CD3+ cells and they were excluded from the tumor cells into the tumor periphery and stroma, and a CD68+ macrophage population predominated." (PMID 37426669, 2023). "Consistent with a clinical trial of CRC patients, metformin treatment significantly decreased the rate of M2 macrophages in the tumor defined by CD163+/ CD68+ expression." (PMID 37686159, 2023). "To validate our findings, we performed immunohistochemical labeling of T cells (CD3), B cells (CD20), myofibroblasts (αSMA), and macrophages (CD68) on sections of primary tumor tissue from our original cohort." (PMID 36881486, 2023). "Membranous GSDMD expression is associated with CD68+ macrophages in the tumor center and CD8+ T cells in the tumor front, whereas nuclear GSDMD exhibits the opposite association." (PMID 38066523, 2023). "The cell density of CD45+ leukocytes and CD68/CD163 subsets was generally higher in the stroma than in tumor nests (HNSCC) or squamous epithelium (controls)." (PMID 38322012, 2023). "To characterize TME features in the two groups along the treatment, we quantified the presence of CD4+ T cells, CD8+ T cells, and CD68+ macrophages in patients’ tumor samples using multiplex IHC." (PMID 37769655, 2023). "CD68loCD163hi cells predominantly consist of DCs, are relatively uniformly distributed in the tumor stroma, express relatively little PD-L1 compared with the other two CD68/CD163 subsets, and interact rarely with PD-1-expressing T cells." (PMID 38322012, 2023).
tumor (continued). "The lymphoid biomarker panel depicts CD3+ T cells, CD3+CD8+ cytotoxic T cells, and CD3+FOXP3+ regulatory T cells (Tregs), while the myeloid biomarker panel shows CD68+ macrophages; the tumor cells were stained for PanCK/SOX10." (PMID 36900182, 2023). "In another study analyzing biopsies of liver metastases from PDAC patients, metastatic tumor cells were also surrounded by CD68+ macrophages which was the most prominent immune cell population, underlining the results of our study." (PMID 37449210, 2023). "As biomarkers for the tumor microenvironment (TME), CD163 and CD68 (tumor-infiltrating macrophages—TAM), as well as CD34 and CD105 (intratumoral microvascular density—IMVD), were chosen." (PMID 37296922, 2023). "Analysis of the tumor microenvironment of lung metastatic loci in mice injected with control LC cells revealed a substantial increase in MAMs, including CD68+ M1 and CD206+ M2 macrophages as compared to those injected with SCEL-downregulated LC cells." (PMID 38037106, 2023). "It has been now accepted that TAM is mainly composed of the M2 phenotype, and our IHC results also confirmed that the CD68-positive macrophages in the tumor microenvironment were also positive for CD206, suggesting that they are of the M2 phenotype." (PMID 38097649, 2023). "Within the tumor, an average of 4.93% was covered by CD68-immunopositive macrophages and 1.33% by CD3-immunopositive T-lymphocytes." (PMID 37237550, 2023). "We identified higher proportions of CD163+ and CD68+163+ TAMs in tumour tissue than in healthy adjacent tissue (t test, p < 0.01)." (PMID 35963900, 2023). "To characterize potential responses from NPCs upon their interaction with tumor cells, we compared the αSMA, CD68 and CK19 IHC of 7-day co-SphWLC:T with that of 7-day co-SphWLC aggregated in suspension without SphT." (PMID 36728410, 2023). "Tumor stage was also significantly correlated with immune cell densities: we observed significantly higher densities of CD16a+, and CD68+CD16a+ cells in the stromal compartments of stage IV compared with stage III HGSC tumors." (PMID 38318505, 2023). "Similar to the examination of PD-L1 in the TME, we found that TAMs, but not tumor cells, promote the total microenvironmental pool of CD68 to a greater extent, which can be used to engage PD-1-positive T cells in the vicinity of tumor cells." (PMID 36900182, 2023). "A lesser number of CD68+ TAMs were also reported in cancer patients where the tumor cells migrated and invaded the blood circulation, lymph vessels, and perineural tissues." (PMID 37525217, 2023). "Meanwhile, it is well known that tumor-associated macrophage (TAM, CD68+ or CD163+) infiltration in tumors is associated with poor prognosis in cancer patients." (PMID 37259060, 2023). "Conversely, higher CD68+ TAMs density in tumor nest (TN) or TN/TS ratio of CD68+ TAMs predicted better OS (all P<0.05)." (PMID 36633963, 2023). "CD4+ T cells were significantly association with all the other tumor-associated immune cells (TAIs) including CD8, CD68 and CD206 positive cells." (PMID 37405518, 2023). "Further multiplexed immunofluorescence staining of the CD3/CD4/CD8A/CD68/CCL4 markers validates the immune-activated state in the tumor thrombus samples." (PMID 37244923, 2023). "They compute mean cell densities of CD8+, CD20+, and CD68+ in intra-tumoral tissue and within the tumour–stroma interface zone (IZ), which includes tumour, tumour edge and stroma." (PMID 36183010, 2023). "the high CD68+ TAMs infiltration in the tumor or TS indicated poor OS and DFS, while the higher CD68+ TAMs in TN or TN/TS ratio of CD68+ TAMs was associated with better prognosis." (PMID 36633963, 2023). "While tumor core areas are the major contributor to the overall TSPO signal, TSPO signals in the tumor rim are mainly driven by CD68-positive microglia/macrophages." (PMID 37697350, 2023).